ACE (angiotensin I converting enzyme)
Diseases named in the same sentence as ACE in open-access papers (continued):
Sharing a sentence is not in itself a finding about the gene and the disease.
heart failure (continued). "At last follow-up visit, angiotensin-converting enzyme (ACE) inhibitors/angiotensin II receptor type 1 (AT1) antagonists were prescribed in 31/49 (63%) patients for treatment of reduced RV ejection fraction/heart failure." (PMID 37505269, 2023). "In heart failure patients, an intensive and appropriate therapy with ACE inhibitors or angiotensin receptor/neprilysin inhibitors, beta-blockers, diuretics and sodium-glucose cotransporter-2 inhibitors may slow the progression of the disease." (PMID 36836722, 2023). "Two trials have evaluated whether angiotensin receptor–neprilysin inhibitors (ARNIs) are associated with better cognitive function relative to an angiotensin-converting enzyme (ACE) inhibitor or angiotensin receptor blocker in participants with heart failure." (PMID 38068464, 2023). "Another study evaluating the effects of ACE inhibitors, ARBs, and mineralocorticoid receptor antagonists (MRAs) in heart failure patients on soluble plasma concentrations of ACE2 found that ACE inhibitor or ARB use was not a strong predictor of elevated circulating ACE2 levels." (PMID 36985188, 2023). "Although angiotensin converting enzyme (ACE) inhibitors are considered useful for the treatment of human heart failure, some experimental failing-heart models have shown little beneficial effect of ACE inhibitors in animals with poor oral health, particularly periodontitis." (PMID 37983238, 2023). "Note that initial low-dose ACE inhibitors usually provide the full anti-hypertensive effects, while the up-titration of the drug is important to improve long-term efficacy and surrogate endpoints, such as in heart failure." (PMID 38137544, 2023). "This study presents a thorough and up‐to‐date meta‐analysis of clinical studies aimed at evaluating the safety and effectiveness of sacubitril‐valsartan in comparison to RAAS inhibitors (ACE inhibitors or ARBs) as standalone treatments for patients diagnosed with heart failure." (PMID 38013641, 2023). "The recommended treatment for heart failure is the same used in other etiologies, and relies on the use of beta blockers, angiotensin converting enzyme (ACE) inhibitors, diuretics, aldosterone antagonist and digoxin or the combination of hydralazine with isosorbide nitrate." (PMID 38188583, 2023). "For her dilating cardiomyopathy, no apparent cause was found and heart failure medical therapy [including diuretics, angiotensin-converting enzyme (ACE) inhibitors and low dosages of beta blockade] were initiated." (PMID 36755312, 2023). "ACE inhibitors have a role in protecting from adverse cardiac remodeling and heart failure and might be one of the measures to reduce cardiac events." (PMID 37308130, 2023). "In addition to their antihypertensive actions, beta-blockers are used to manage arrhythmias and treat angina pectoris and heart failure, while ACE inhibitors provide cardioprotection in patients with acute coronary syndromes and treat congestive heart failure." (PMID 34533690, 2023). "All patients also received appropriate therapy for heart failure with beta-blockers, angiotensin receptor–neprilysin inhibitors/ACE inhibitors/angiotensin receptor blockers, mineralocorticoid receptor antagonists and diuretics according to current ESC Guidelines." (PMID 37373705, 2023). "Consequently, prevention or attenuation of cardiac hypertrophy and transition into heart failure is a major goal of ACE inhibitor therapy." (PMID 36551815, 2022). "Customarily ‘preventative medicines’ such as beta-blockers (for angina or rate control in atrial fibrillation), ACE inhibitors (for heart failure) and calcium channel blockers (for angina) could also be prescribed for symptom control." (PMID 35906504, 2022). "The most well-studied therapies include conventional heart failure therapies, including angiotensin converting enzyme (ACE) inhibitors and beta blockers, and dexrazoxane; additionally, there are multiple investigational treatments currently undergoing evaluation." (PMID 35528842, 2022).
heart failure (continued). "Also, it is difficult to pre-screen for confounding factors like stroke, arrhythmias, heart failure, and the use of ACE inhibitors." (PMID 35808551, 2022). "The search strategy included a combination of the following keywords: “heart failure with preserved ejection fraction”, “beta-blockers”, “ACE inhibitors”, “angiotensin receptor blocker”, “aldosterone receptor blockers”, “randomized control trial”, “cardiovascular outcomes”, and “mortality”." (PMID 36148200, 2022). "In support, ACE inhibitor treatment alone has been demonstrated to improve 6‐min walking distance in elderly people with functional impairment and heart failure." (PMID 35822425, 2022). "Therefore, the neurohormonal blockade using ACE inhibitors, angiotensin receptor blockers, and beta-blockers mitigates heart failure-induced cardiac remodeling." (PMID 35126818, 2022). "Unsurprisingly, rates of heart failure medication utilization—including ACE-inhibitors, angiotensin receptor blockers, and beta blockers—were higher in the NICM cohort; further studies are needed to better assess the impact of modern heart failure therapies on microvascular function in NICM." (PMID 36399465, 2022). "Heart failure medications, including β-blockers, angiotensin-converting enzyme (ACE) inhibitors/angiotensin receptor blockers (ARBs), spironolactone, diuretics, and digoxin, were more frequently used during the follow-up period in the RV dysfunction group than in the controls (all p < 0.05)." (PMID 35174234, 2022). "A novel combination drug, sacubitril/valsartan marked by Novartis under the name Entresto®, has been shown to be more efficient in reducing cardiovascular events and death, but also heart failure readmission compared to conventional angiotensin-converting enzyme (ACE) inhibition." (PMID 36419097, 2022). "Yet, to date, DMD patients receive non-specific heart failure treatments, beta-blockers, or ACE inhibitors, largely due to a lack of understanding of the mechanisms underlying the cardiac failure." (PMID 34019816, 2021). "The increased expression of the ACE2 in heart failure may serve as a compensatory mechanism, counterbalancing the over‐activity of the deleterious isoform, ACE." (PMID 33660945, 2021). "hATTR should be considered in older persons who have been hospitalized for heart failure, elevated troponin or N-terminal pro-brain natriuretic peptide (NT-proBNP) and intolerance of angiotensin-converting enzyme (ACE) inhibitors, angiotensin receptor blockers, or β blockers." (PMID 34658264, 2021). "Consequently, recommended treatment modalities of heart failure include an inhibitor of the angiotensin converting enzyme (ACE) or an angiotensin II AT1 receptor blocker, ARB." (PMID 34576047, 2021). "This will distinguish our study from the Prospective ARNI vs. ACE Inhibitor Trial to DetermIne Superiority in Reducing Heart Failure Events After MI (PARADISE‐MI), which is enrolling patients up to 7 days after acute infarction and does not require all patients to have LVSD." (PMID 33305513, 2021). "The increased expression of the beneficial ACE2 and of furin in compensated heart failure may serve as a compensatory response to the over‐activity of the deleterious isoform, namely, ACE." (PMID 33660945, 2021). "There is some evidence, for example, suggesting that angiotensin converting enzyme (ACE) inhibitors may positively impact sleep in heart failure patients." (PMID 34063838, 2021). "Moreover, betablockers and angiotensin converting enzyme (ACE) inhibitors are indicated in patients with reduced LVEF according to heart failure guidelines." (PMID 34365980, 2021). "Indeed, evidence suggests that angiotensin-converting enzyme (ACE) inhibitors slow heart failure progression and improve hemodynamics." (PMID 33923899, 2021).
heart failure (continued). "This study concluded that the use of a thiazide diuretic associated or not with an ACE inhibitor resulted in a 30% reduction in stroke risk, 39% in fatal stroke, 21% in all-cause mortality, and 64% in heart failure." (PMID 34946233, 2021). "The increased expression of tissue‐protective ACE2 in heart failure may serve as a compensatory response to the over‐activity of the deleterious isoform, namely, ACE." (PMID 33660945, 2021). "HF treatment consists of modulators of blood pressure such as β-receptor blockers, angiotensin II receptor blockers and angiotensin-converting enzyme (ACE) inhibitors, but the development of adverse post-MI remodeling with progression to heart failure is still high." (PMID 34445425, 2021). "The rationale for use of standard heart failure medications such as angiotensin-converting enzyme (ACE) inhibitors and beta-blockers is largely extrapolated from the adult experience with limited pediatric data, especially specific to pediatric patients with CCM." (PMID 34682138, 2021). "Drugs affecting the renin–angiotensin–aldosterone axis, such as ACE inhibitors, angiotensin receptor blockers, or mineralocorticoid receptor blockers, are used as the primary means of treatment in patients with heart failure and reduced ejection fraction, including those with DCM." (PMID 32599970, 2020). "The relatively hypothetical risk of worsening COVID-19 does not justify discontinuing or switching ARBs or ACE inhibitors due to the specific risk of destabilizing blood pressure control, stroke, heart attack, or worsening heart failure." (PMID 32415494, 2020). "The diversity of its beneficial effects as well as the satisfactory results obtained in previous studies set CoQ10 as the first treatment to improve survival in heart failure patients ahead of angiotensin-converting enzyme (ACE) inhibitors and β-blockers more than a decade ago." (PMID 33182646, 2020). "Pathogenetic heart failure medical treatment was prescribed as follows: Angiotensin-converting enzyme (ACE) inhibitors or angiotensin II receptor blockers (ARB) were received by 69.7%, beta-adrenoceptor blockers by 81.9%, and mineralocorticoid antagonists by 66.7% of patients." (PMID 31948001, 2020). "ACE inhibitors are a standard heart failure medication, targeting a range of physiologic processes to mediate adverse remodeling and improve cardiac function by reducing pre- and afterload, and dampening neurohumoral activation upstream of the myocardium to improve ejection fraction." (PMID 32125488, 2020). "In the present study, an urban cohort of CD in the Northeast of Brazil wasstaged according to the I Latin American Guideline for CD8, and theprevalence of ACE I/D polymorphism in the absence of heart failure wasevaluated." (PMID 32638886, 2020). "ACE inhibitors are widely used in the management of heart failure in the last three decades." (PMID 33488934, 2020). "ACE inhibitors and β-blockers are the recommended first-line treatment for symptomatic heart failure with reduced ejection fraction; if patients remain symptomatic with an LVEF of 35% or below, a mineralocorticoid receptor antagonist may be added." (PMID 30808934, 2019). "Moreover, an angiotensin-converting-enzyme (ACE) inhibitor and angiotensin receptor blocker can also improve cardiac function in heart failure in the rat model." (PMID 30669571, 2019). "In patients with a proven increased risk of death based on cardiovascular risk stratification during hospitalization, treatment with ACE inhibitors (or angiotensin AT1 blockers), beta-blocker therapy, and aldosterone antagonists are indicated when EF LK is ≤40% and/or there is heart failure." (PMID 31781298, 2019). "Since increased activity of angiotensin II is the major factor responsible for heart failure, it is possible that coenzyme Q10 may benefit by decreasing ACE level and angiotensin II levels in patients with left ventricular dysfunction." (PMID 30044377, 2018).
heart failure (continued). "Heart failure is commonly treated with medications such as ACE-inhibitors, aldosterone-antagonists, beta-blockers, and diuretics, however, these drugs also increase the risk of orthostatic hypotension, dizziness, fall, fracture, and also dehydration and hyponatremia." (PMID 29337859, 2018). "ACE inhibitors also decrease peripheral vascular resistance, improve endothelial function, prevent myocardial fibrosis and reduce afterload, all of which delay the progression of heart failure." (PMID 28338606, 2017). "Therefore, palliative treatment for heart failure due to diastolic dysfunction was begun with diuretics (furosemide, 0.5 mg/kg/day), a β-blocker (bisoprolol fumarate, 0.625 mg/day), and an ACE inhibitor (enalapril, 2.5 mg/day)." (PMID 28316854, 2017). "Changes in the angiotensin-converting enzyme (ACE) gene may contribute to theincrease in blood pressure and consequently to the onset of heart failure(HF)." (PMID 28977050, 2017). "Besides the conventional therapy for heart failure, the diuretics, cardiac glycosides and ACE-inhibitors, current pharmacotherapy includes beta-blockers, mainly because of their pathophysiological mechanisms upon heart remodeling." (PMID 27275338, 2016). "Renin, angiotensinogen, ACE, and Ang II receptors were all present in the heart, where they were found upregulated in models of cardiac injury, such as volume overload, myocardial infarction, and heart failure." (PMID 27652272, 2016). "Additionally, chronic use of a beta-blocker in conjunction with ACE inhibitor therapy improved clinical status and exercise tolerance in patients with heart failure." (PMID 26809174, 2016). "Pharmacologic interventions such as angiotensin converting enzyme (ACE) inhibitors, angiotensin receptor antagonists (ARBs) and beta blockers are known to benefit patients with heart failure (HF) and reduced left ventricular ejection fraction (LVEF) complicating acute myocardial infarction (MI)." (PMID 26060129, 2015). "The increased hip fracture risk in people younger than 80 years using loop diuretics and plain ACE inhibitors, however, may possibly be due to the “more-ill-user effect” as these drugs are frequently issued to relatively frail people with heart failure." (PMID 26626043, 2015). "Thus, the study discloses a new aspect of beneficial action of orally administered ACE inhibitors in the postinfarct cardiac failure and during chronic exposure to stress." (PMID 25045668, 2014). "Thus, in patients who were promptly treated with an ACE inhibitor, immediately following acute myocardial infarction, a significant reduction in death, development of heart failure, and subsequent repeated myocardial infarction were found." (PMID 24600438, 2014). "We did, however, adjust for use of ACE inhibitors and loop diuretics as a proxy of heart failure, and there is the possibility that these variables may have mediated some of the effect of BMI." (PMID 24885137, 2014). "Although there are several cardioprotective drugs for treating heart failure and cardiac hypertrophy, such as beta-adrenergic receptor blocker, ACE inhibitor, and calcium channel blockers, the mobility and mortality of heart failure and cardiac hypertrophy were still high in the United States." (PMID 25093027, 2014). "In this case series, we discuss an alternative approach in selected patients with severe cardiogenic shock to use a VA-ECMO as bridge-to-recovery, enhanced by introducing very early heart failure medication, including ACE inhibitors and beta blockers using enoximone and ECMO." (PMID 24424723, 2014). "Moreover, although ACE expression was lower in patients with heart failure before CRT, this general relationship disappeared after CRT, when an improvement was observed in the clinical parameters." (PMID 24691269, 2014). "Moreover, despite complete vascular ACE inhibition plasma aldosterone levels are elevated in patients with heart failure." (PMID 23909633, 2013).
heart failure (continued). "Alternately, an increase in prevalence of comorbidities such as heart failure and chronic kidney disease, again associated with AKI and with prescribing of ACE inhibitors and ARAs, might also be expected to explain some of the association." (PMID 24223154, 2013). "Since beta-blocker and ACE inhibitors were previously shown to mediate a positive influence on cachexia in heart failure, this treatment might also reduce myostatin expression." (PMID 24260393, 2013). "However, despite optimal medical treatment with ACE inhibitors or Angiotensin-II receptor blockers, many patients develop adverse remodeling and heart failure." (PMID 23630610, 2013). "The affected family members presented typical clinical features consistent with DCM, with left ventricular dilatation and systolic dysfunction, responding to heart failure medication including beta-blockers and ACE-inhibitors during the long-term follow-up (ranging from 6 to 25 years)." (PMID 24205113, 2013). "In spite of the integration of various medical regiments, such as ACE-inhibitors, β-blockers, the morbidity and mortality of heart failure patients remain staggeringly high, in which more than 80% of heart failure patients have to be hospitalized; 50% of which die within 5 years of the diagnosis." (PMID 23826926, 2013). "ACE inhibitors have been prescribed for hypertensive patients worldwide, and many clinical application data have demonstrated that ACE inhibitors significantly reduce the morbidity and mortality of patients with myocardial infarction or heart failure." (PMID 25937975, 2013). "Furthermore, the combined endpoint of death and heart failure hospitalization was reduced by the addition of an ACE inhibitor to standard care in patients with asymptomatic LVSD, which translated to improved long-term survival." (PMID 24278681, 2012). "Subsequent studies have demonstrated similar benefits from angiotensin receptor blockers in the setting of heart failure associated with LVSD, either as an alternative to ACE inhibitors, in patients who were previously intolerant of ACE inhibitors, or in addition to ACE inhibitor therapy." (PMID 24278681, 2012). "The prevalence of possible influencing factors including gender, body mass index (BMI), anemia and medications for heart failure such as ACE inhibitors, angiotensin-receptor blockers, beta blockers, but in the present study, we didn’t find the correlation between BNP and all of them." (PMID 22834778, 2012). "The effect of ACE-inhibitors is counteracted by aspirin, suggesting that bradykinin metabolism has a role, and bradykinin is likely to participate to abnormal alveolar capillary gas diffusion regulation in heart failure." (PMID 23365739, 2012). "Several studies have shown that ACE inhibitors improved exercise capacity in both younger and older people with heart failure but caused no improvement in grip strength." (PMID 22500226, 2012). "Over 90% of newly referred heart failure patients with LVSD now receive ACE inhibitors and beta blockers in our service, however only one quarter of patients who are not on target doses of therapy when they leave hospital will achieve target doses by 6 months (unpublished data)." (PMID 24278681, 2012). "Further, nearly two-third of the subjects were taking drugs such as diuretics and ACE inhibitors and prescription items for ACE inhibitors and AIIRAs have been increasing that may potentially have alleviated progression to heart failure." (PMID 22110591, 2011). "Prevention of pulmonary venous contraction by AT1 antagonists or ACE-inhibitors might contribute to their beneficial effect in heart failure." (PMID 22216346, 2011). "With a relatively poor prognosis and an increased likelihood of subsequent all-cause and CHD-related mortality being found for this cohort, heart failure was found in proportionally more patients receiving ACE-inhibitors than those that didn't receive the therapy." (PMID 22028911, 2011).